GAS5 (growth arrest specific 5)
Diseases named in the same sentence as GAS5 in open-access papers (continued):
Sharing a sentence is not in itself a finding about the gene and the disease.
breast carcinoma (continued). "Reportedly, GAS5 is abnormally expressed in leukemia, cervical cancer, breast cancer, ovarian cancer, prostate cancer, bladder cancer, gastric cancer, colorectal cancer, liver cancer, osteosarcoma, glioma and lung cancer, and it exerts a tumor-suppressive effect in cancers." (PMID 34022918, 2021). "By suppressing miR-222, GAS5 can increase the efficiency of tamoxifen in breast cancer." (PMID 34202777, 2021). "The authors also confirmed the suppressor function of lncRNA GAS5 in breast cancer." (PMID 34202777, 2021). "GAS5 is thus a promising target in the treatment of breast cancer patients." (PMID 34202777, 2021). "Thus, GAS5 contains multiple MREs for binding these oncogenic miRNAs in the upregulation of suppressor proteins in breast cancer." (PMID 34202777, 2021). "For example, GAS5 and miR-21 are characterized by mutual repression in breast cancer cells." (PMID 34202777, 2021). "Moreover, suppressive lncRNA GAS5 and regulating suppressive proteins play a critical role in enhancing the sensitivity of breast cancer patients to multiple drugs." (PMID 34202777, 2021). "LncRNA GAS5 is downregulated in multiple cancers and acts as a tumor suppressor in breast cancer." (PMID 34202777, 2021). "GAS5 is downregulated in multiple cancers and acts as a tumor suppressor in breast cancer." (PMID 34202777, 2021). "How significant the effect of GAS5 is on metastasis in breast cancer remains unanswered." (PMID 34202777, 2021). "There are also some indirect arguments for the influence of GAS5 on breast cancer metastasis." (PMID 34202777, 2021). "Current knowledge thus implicates GAS5 as a promising therapeutic target in breast cancer." (PMID 34202777, 2021). "In HER2-positive breast cancer, silencing of GAS5 contributes to trastuzumab resistance." (PMID 34527584, 2021). "Autophagy and GAS5 expression were both decreased in breast cancer cells." (PMID 32517694, 2020). "In addition to downregulating tamoxifen resistance, GAS5 exerts tumor-suppressive effects in breast cancer via several pathways." (PMID 32486413, 2020). "Furthermore, GAS5 has been linked to trastuzumab resistance, which is a main obstacle in HER2-positive breast cancer cells." (PMID 33076450, 2020). "The GAS5-miRNA-222 axis can also influence sensitivity to tamoxifen in breast cancer." (PMID 31979312, 2020). "Overall, GAS5 is also considered to function as a tumor suppressor in breast cancer." (PMID 33076450, 2020). "GAS5 contains a hormone response element that can induce cell apoptosis in breast cancer." (PMID 33308258, 2020). "It has been shown that GAS5 and miR-21 are likely in the same AGO2 complex, and GAS5 could act as a ceRNA to sponge miR-21 in breast cancer cells." (PMID 33203802, 2020). "Therefore, inhibiting the expression of GAS5 in breast cancer cells can improve the their survival rate in a barren environment, suggesting that increasing the expression of GAS5 can be used to treat breast cancer." (PMID 32771923, 2020). "For example, lncRNA GAS5 induces cell apoptosis in breast cancer has been reported." (PMID 31400752, 2019). "In addition, the chemotherapeutic drug, Lapatinib, can also enhance the response of breast cancer cells to trastuzumab by inducing GAS5 expression." (PMID 31750253, 2019). "In a variety of tumors, including lung, liver, colorectal, and breast cancer, the expression of GAS5 is significantly decreased, suggesting that GAS5 might be a tumor-suppressing lncRNA." (PMID 31480503, 2019). "Recently, lncRNAs such as lncRNA-ATB, GAS5, HOTAIR, CCAT2, H19, BCAR4, UCA1, LncRNA-ROR and LncRNA-ARA have been implicated in resistance to chemotherapy in breast cancer patients." (PMID 29299178, 2017). "Knockdown of GAS5 resulted in increased resistance to docetaxel and 5-FU in breast cancer cells." (PMID 28430163, 2017).
breast carcinoma (continued). "In contrast, growth arrest-specific 5 (GAS5) is down regulated in breast cancer and hepatocellular carcinoma, and maternally expressed 3 (MEG3) is downregulation in meningioma and colorectal cancer, indicating that these two lncRNAs are involved in tumor suppression." (PMID 27999202, 2017). "Several studies have demonstrated that GAS5 is down-regulated in gastric, glioma, stomach, lung, cervical, liver, gallbladder, pancreatic, prostate and breast cancer." (PMID 29299178, 2017). "Reduction of GAS5 will attenuate drug-induced death in breast cancer cells." (PMID 27732939, 2017). "Subsequently, gas5 was identified as a tumor suppressor, and prognosis marker in renal cell carcinoma, cervical cancer, malignant pleural mesothelioma, gastric cancer, colorectal cancer, endometrial cancer, and breast cancer." (PMID 29207621, 2017). "Thus, the GAS5 lncRNA HREM sequence alone is sufficient to induce apoptosis in breast cancer cells, including triple-negative breast cancer cells." (PMID 26862727, 2016). "GAS5 lncRNA is down-regulated in multiple cancers, including breast cancer." (PMID 26862727, 2016). "The lncRNA growth arrest special 5 (GAS5), which was located at 1q25, was identified to be down-regulated and functions as a tumor suppressor gene in many kinds of cancers, including breast cancer, prostate cancer, pancreatic cancer, bladder cancer, lung cancer, gastric cancer, and so on." (PMID 27863421, 2016). "In order to address these questions, we have examined if the GAS5 HREM sequence alone is sufficient to promote the apoptosis of breast cancer cells, both basally and upon the application of an apoptotic stimulus, and how the resulting cellular responses compare with those of mature GAS5 lncRNA." (PMID 26862727, 2016). "The involvement of GAS5 in human cancers was first studied in breast cancer." (PMID 27608009, 2016). "This study may provide a strategy and facilitate the development of GAS5 directed diagnostics and therapeutics against trastuzumab-resistant breast cancer." (PMID 27034004, 2016). "That indicates that GAS5 is reduced by trastuzumab and may act as a tumor suppressor in trastuzumab-resistant breast cancer." (PMID 27608009, 2016). "Moreover, GAS5 promotes cell proliferation and /or apoptosis in different cell types, including breast cancer cells and its tumor suppressor role is indicated by its inhibition of breast tumor growth." (PMID 27608009, 2016). "Transcript levels of GAS5 were decreased in most breast cancer tissues." (PMID 27034004, 2016). "Not all treatments show dependence on GAS5 lncRNA for their action, insofar as imatinib-induced death of breast cancer cells is unaffected by GAS5 silencing, however the action of another tyrosine kinase inhibitor, gefitinib, shows GAS5-dependence in lung cancer cells." (PMID 26198250, 2015). "Moreover, in breast cancer cells, miR-21 was shown to target and hence downregulate the expression of a tumour suppressor lncRNA, GAS5." (PMID 26410378, 2015). "One reason might be that primers recognizing all GAS5 ESTs were used in the breast cancer study, while in our case primers were recognizing only 20 out of 29 different splice variants, which nevertheless included the splice variants detected in cancer cells." (PMID 24885398, 2014). "GAS5 levels are also significantly reduced in breast cancer samples." (PMID 24069260, 2013). "Previous studies showed that GAS5 controls cell apoptosis and is downregulated in breast cancer." (PMID 24069260, 2013). "Additionally, the sponging of miR-221 via GAS5 has been demonstrated to mitigate Adriamycin resistance in breast cancer, specifically through the upregulation of Dickkopf 2 (DDK2) and suppression of P-glycoprotein (ABCB1) expression and the Wnt/β-catenin pathway." (PMID 39941145, 2025).
breast carcinoma (continued). "In conclusion, GAS5 represses the growth of breast cancer through regulating the IGF2BP2/QKI pathway, and this inhibitory effect is modulated by FTO-mediated m6A modification, suggesting that the FTO/GAS5/IGF2BP2/QKI pathway may be a potential target for breast cancer treatment." (PMID 38782769, 2024). "Thus, reduced expression of GAS5 in MDR breast cancer cells could upregulate Wnt/β-catenin signaling and induce the MDR transporter ABCB1 expression." (PMID 39403602, 2024). "Moreover, we found that GAS5 was more lowly expressed in breast cancer cell lines." (PMID 38782769, 2024). "Therefore, the drugs may exert antiproliferative effects on leukemia, gastric cancer, and breast cancer cells by modulating the GAS5–miR-222-3p/miR-222-3p/miR-196a-5p axis." (PMID 37190145, 2023). "In addition, the GAS5 is a potential target for breast cancer treatment." (PMID 36011604, 2022). "The lncRNA growth arrest-specific 5 (GAS5) played an important role in the development of digestive system tumors, and its polymorphic site rs145204276 might induce the promoter activity of lncRNA GAS5 to protect against the development of breast cancer." (PMID 36045445, 2022). "Moreover, in breast cancer, as in other types of cancer, the suppression of mTOR and GAS5 may be mutual." (PMID 34202777, 2021). "Importantly, through these interactions, lncRNA GAS5 may increase sensitivity to different drugs and enhance the chemotherapy treatment of breast cancer patients." (PMID 34202777, 2021). "In addition, GAS5 expression was significantly downregulated in trastuzumab-resistant breast cancer patients, gefitinib-resistant lung adenocarcinoma cell lines and erlotinib-resistant glioma cell line, which was of great clinical significance for targeted therapy." (PMID 28977945, 2017). "Additionally, GAS5 overexpression could sensitize breast cancer cells to doxorubicin combined with UV treatment, and the role of GAS5 in re-sensitizing cells to doxorubicin has since been confirmed in bladder cancer." (PMID 28430163, 2017). "The lncRNA growth arrest special 5 (GAS5), a pivotal tumor suppressor long noncoding RNA in human cancers, has been identified to be involved in carcinogenesis progress of several cancers, including breast cancer, prostate cancer, hepatocellular carcinoma, and colorectal cancer." (PMID 29207621, 2017). "Conversely, GAS5 could control cell growth and is down-regulated in breast cancer." (PMID 28423699, 2017). "Also GAS5, whose transcript levels were significantly reduced in breast cancer samples relative to adjacent unaffected normal breast epithelial tissues, could controls apoptosis and down-regulated in breast cancer." (PMID 27863421, 2016). "At the same time, many lncRNAs act as tumor suppressors, such as GAS5 (growth arrest-specific 5) and BC069792 in breast cancer." (PMID 40149492, 2025). "Of note, growth arrest-specific transcript 5 (GAS5) is considered a tumor-suppressor lncRNA whose expression is downregulated in various cancers, including non-small cell lung carcinoma (NSCLC), breast carcinoma, and hepatocellular carcinoma (HCC)." (PMID 39958058, 2025). "Studies have indicated that overexpression of GAS5 enhances ADR sensitivity, induces cell apoptosis, and inhibits the function of ABCB1, offering the potential to overcome chemotherapy resistance in breast cancer patients." (PMID 40125243, 2024). "LncRNA GAS5 expression decreased in breast cancer and was regulated by FTO-mediated m6A modification in an IGF2BP2-dependent manner, resulting in decreased GAS5 stability and expression." (PMID 38782769, 2024). "Elevated levels of ABCB1 and reduced levels of growth arrest-specific 5 (GAS5), a lncRNA, were observed in resistant breast cancer cells and tissues." (PMID 38413011, 2024). "RNA sequencing analysis has revealed the downregulation of GAS5 and upregulation of ABCB1 in ADR-resistant breast cancer tissues and cells." (PMID 40125243, 2024).
breast carcinoma (continued). "The results revealed that some circulating lncRNAs (MEG3, NBAT1, NKILA, GAS5, EPB41L4A‐AS2, Z38, and BC040587) were significantly down‐regulated in breast cancer patients compared to healthy women." (PMID 36274054, 2023). "Bharangin, curcumin, gambogic acid, and corylin upregulate growth-arrest-specific 5 (GAS5) levels of B lymphocytic leukemia, gastric cancer, and breast cancer cells." (PMID 37190145, 2023). "First, we assessed the expression of GAS5 in MCF-7 and MDA231 breast cancer cells and MCF-10A normal cells." (PMID 35059460, 2022). "LncRNA GAS5 regulates autophagy in breast cancer through the GAS5-miR-23a-ATG3 axis, and GAS5 expression is down-regulated in breast cancer." (PMID 35813295, 2022). "For example, MALAT1, HOTAIR, lincRNAp21, GAS5, TUG1, and ncRNA-CCND1 were identified in EVs derived from human cervical and breast carcinomas." (PMID 35250537, 2022). "Though we already described how GAS5 expression can lead to TRAIL activation, TRAIL’s role in autophagy in breast cancer should be noted separately." (PMID 34202777, 2021). "This work identified lncRNA GAS5 as a novel prognostic marker and candidate drug target for HER2+ breast cancer." (PMID 34938660, 2021). "The activation of mTOR was accompanied by decreased expression of GAS5 and PTEN (mediated by miR-21), leading to an increase in the resistance of breast cancer patients to trastuzumab." (PMID 34202777, 2021). "Plasmid (pcDNA-GAS5)-overexpressing GAS5 increased MCF-7/ADR apoptosis and reversed breast cancer cell chemoresistance to ADR-based chemotherapy in vitro." (PMID 34202777, 2021). "The expression of GAS5, similar to that of several other oncosuppressive lncRNAs, is inhibited by c-MYC, which is amplified in 15% of breast cancer cases." (PMID 34202777, 2021). "A negative correlation was established between the expression levels of GAS5 and miR-21 in MCF-7 and MDA-MB-231 cells and clinical breast cancer samples." (PMID 34202777, 2021). "In a human breast cancer cell line (MCF7), a lncRNA called Growth Arrest Specific 5 (GAS5) facilitates the transcription of TRAIL [transcription of tumor necrosis factor (TNF)-related apoptosis-inducing ligand] mRNA." (PMID 33419460, 2021). "In breast cancer, the suppression of PTEN, the expression of which is enhanced by GAS5, attenuates not only apoptosis but also autophagy." (PMID 34202777, 2021). "GAS5 is mainly identified as a well-characterized tumor suppressor, and is downregulated in a wide range of human malignancies, including lung cancer, renal cell carcinoma, breast cancer, and bladder cancer, indicating that GAS5 could be utilized as a potential diagnostic hallmark." (PMID 32354045, 2020). "Notably, Koldemir and colleagues have demonstrated that GAS5 accumulates in exosomes in response to proapoptotic signals in breast carcinoma cells hypothesizing that this transcript could be involved in the communication of tumour cells upon cell death-promoting signals." (PMID 32967315, 2020). "For instance, GAS5 is downstream of the NOTCH signaling pathway, which can promote the proliferation of breast cancer cells." (PMID 33291485, 2020). "Among the most affected ncRNAs, we found that sorafenib mediated the dysregulation of the lncRNAs GAS5, HOTTIP and HOXA-AS2 and the miR-126-3p, in a panel of human cancer cell lines (HCC, renal and breast carcinomas)." (PMID 31235746, 2019). "Expressional analysis of primary breast cancer tissue and breast cancer cell lines (i.e., MDA-MB-23l, MDAMB-453, BT549, SK-BR-3, and MCF-7) demonstrated down-regulation of GAS5 expression." (PMID 31597272, 2019). "For example, growth arrest-specific transcript 5 (GAS5), has also been shown to be expressed at low levels in breast cancer tissues, GAS5’s overexpression in breast cancer cell lines induced apoptosis and suppressed proliferation." (PMID 30828265, 2019).
breast carcinoma (continued). "The lncRNA growth arrest-specific transcript 5 (GAS5) (NCBI GeneID: 60674) is downregulated in several kinds of cancers, including cervical cancer and breast cancer, and HCC tissues." (PMID 31620370, 2019). "LncRNA growth arrest specific transcript 5 (lncRNA GAS5) is downregulated in NSCLC, breast cancer and HCC tissues, and lncRNA GAS5 knockdown repressed cell viability." (PMID 30217221, 2018). "The expression levels of GAS5 and PTEN mRNA in the same set of 86 breast cancer tissues were measured." (PMID 27034004, 2016). "Further study declares that GAS5 is downregulated in SKBR-3/Tr cells and breast cancer tissue from trastuzumab-treated patients, while lapatinib can upregulate GAS5 targeting of PTEN to relieve trastuzumab resistence." (PMID 27897214, 2016). "Expression of the lncRNA GAS5 was decreased in SKBR-3/Tr cells and in breast cancer tissue from trastuzumab-treated patients." (PMID 27034004, 2016). "This work identifies GAS5 as a novel prognostic marker and candidate drug target for HER2-positive breast cancer." (PMID 27034004, 2016). "In summary, GAS5, regulated by mTOR pathway, serves as a ceRNA of miR-21 to regulate PTEN in the development of breast cancer trastuzumab resistance." (PMID 27034004, 2016). "Down-regulation of GAS5 was found in multiple cancers, including CRC, breast cancer and hepatocellular carcinoma." (PMID 27391432, 2016). "The GAS5 transcript level was correlated with PTEN mRNA level and protein level in breast cancer tissues." (PMID 27034004, 2016). "GAS5 (growth arrest-specific 5) was found to be downregulated in breast cancer tissues, and overexpression of this lncRNA in the MCF-7 breast cancer cell line furthered growth arrest and apoptosis." (PMID 25288503, 2014). "The expression of GAS5 was significantly lower in breast cancer tissues than in adjacent noncancerous normal tissues." (PMID 38782769, 2024). "GAS5 recruited IGF2BP2 to target QKI and upregulated QKI expression in breast cancer cells." (PMID 38782769, 2024). "For example, the lncRNA GAS5, which acts as a tumor suppressor via the regulation of various tumor suppressor proteins, such as PTEN, PDCD4, OKK2, FOXO1, and SUFU, is markedly downregulated in breast cancer." (PMID 36810560, 2023). "The GAS5 level in non-malignant breast MCF-10A cells was found to be higher than that in MCF-7 or MDA-MB-231 breast cancer cells, detected using qRT-PCR." (PMID 34202777, 2021). "Bharangin via regulation H19, MEG-3, GAS-5, MHRT, NEAT1 lncRNAs, and suppression NF-κB activity could inhibit migration, proliferation, and cell cycle of breast cancer cell lines." (PMID 33805687, 2021). "GAS5 acts as a competitive endogenous RNA (ceRNA) of miR-21, competitively binding to miR-21 to increase PTEN and promote proliferation and metastasis of trastuzumab-resistant breast cancer cells." (PMID 32390766, 2020). "Regarding endocrine therapy resistance, a previous study using an MCF7-derived tamoxifen-resistant cell line suggests that GAS5 acts as a ceRNA by sponging miR-222 and upregulates PTEN, which is a target of miR-222 and weakens the tamoxifen resistance of breast cancer cells." (PMID 32486413, 2020). "SPRY4-IT1, GAS5, PANDAR and H19 are lncRNAs dysregulated in breast cancer." (PMID 33291485, 2020). "Comparison of breast cancer tissue and surrounding noncancerous tissue confirms that GAS5 levels are reduced in breast cancer tissue." (PMID 31533355, 2019). "Not surprisingly (given GAS5′s tumor suppressor role), low expression of the lncRNA indicates a poor prognosis in glioma and in breast cancer." (PMID 31533355, 2019). "The results obtained in HA22T/VGH cells were in line with the expression profile determined by lncRNA PCR array proving that sorafenib may mediate GAS5 up-regulation in other HCC cells as well as in renal and breast cancer cells." (PMID 31235746, 2019).